FZD6 (frizzled class receptor 6)
Diseases named in the same sentence as FZD6 in open-access papers (continued):
Sharing a sentence is not in itself a finding about the gene and the disease.
glioma (10 papers, 2016 to 2026). A benign or malignant brain and spinal cord tumor that arises from glial cells (astrocytes, oligodendrocytes, ependymal cells). "Deletion of circEXOC6 restrained cell progression and glycolysis by sponging miR-433-3p and interacting with FZD6, which might provide an underlying target for glioma treatment." (PMID 37554539, 2023). "Meanwhile, the high expression of FZD6 indicated poor prognosis not only in GBM but also in gliomas and LGG of TCGA, CGGA, CGGA301, GSE108474 and GSE16011 datasets (except GSE108474-GBM dataset)." (PMID 36932454, 2023). "Through literature research, we screened out five mRNAs (SPARC, YY1, ERBB4, MAP3K2, and FZD6) that are highly expressed in glioma tumor tissues and promote glioma progression." (PMID 37554539, 2023). "CircEXOC6 and FZD6 were highly expressed, while miR-433-3p was significantly lowly expressed in glioma tissues or cells." (PMID 37554539, 2023). "Knockdown of circEXOC6 repressed cell proliferation, migration, invasion, glycolysis, and angiogenesis, as well as promoted cell apoptosis in glioma cells by sponging miR-433-3p and reducing the FZD6 expression level." (PMID 37554539, 2023). "Nevertheless, the various downstream pathways of FZD6 are still elusive in glioma cells, which requires further studies in the future." (PMID 37554539, 2023). "In TCGA, CGGA, CGGA301, GSE108474 and GSE16011 datasets, the expression of FZD6 was elevated in a higher grade of gliomas and GBM had the highest level of FZD6." (PMID 36932454, 2023). "Peng at al reported that in addition to being upregulated in high-grade gliomas, CTHRC1 expression correlated with genes associated with the Wnt Signaling pathway (DVL3, DVL1, DVL2, ROR2, WNT3A, FZD6 and FZD5)." (PMID 36190948, 2022). "Among Wnt ligands, receptors and co-receptors, we found that FZD3, ROR2, and Wnt5a regulate FZD6 overexpression-induced phenotypes in glioma spheres." (PMID 27698350, 2016). "Similarly, the FZD6 expression level was obviously enhanced, and elevated FZD6 reversed miR-433-3p overexpression-suppressed cell progression of glioma, which was coincident with the previous research." (PMID 37554539, 2023). "Hence, the results from our study suggested that the knockdown of circEXOC6 regulated FZD6 by targeting miR-433-3p to restrain the cell progression of glioma, which was hoped to provide a new perspective for glioma treatment." (PMID 37554539, 2023). "Besides, miR-433-3p enrichment inhibited cell progression and glycolysis in glioma, and the effect was reversed by overexpression of FZD6." (PMID 37554539, 2023). "Collectively, our finding strongly demonstrated a crucial role of the FZDs in glioma and proved that FZD2 and FZD6 may be novel independent predictors of poor prognosis in glioma." (PMID 36699699, 2022). "FZD1/2/5/6/7/8 could be an unfavorable prognostic factor in glioma and FZD2 and FZD6 may be novel independent predictors of poor prognosis in glioma." (PMID 36699699, 2022). "Taken together, these findings suggest that FZD2 and FZD6 may serve as independent predictors of poor prognosis in glioma, and FZD1/5/7/8 may be a disadvantageous factor." (PMID 36699699, 2022). "We thus assessed whether FZD6 regulates Wnt signalling and tumorigenicity in glioma spheres." (PMID 27698350, 2016). "Modulation of these miRs that target Wnt inhibitors FZD6 and APC affects nuclear localization of β-catenin in both PN and MES glioma spheres." (PMID 27698350, 2016). "Additionally, tumor treating fields (TTF) -mediated downregulation of circMMD can inhibit glioma progression by the FUBP1/FIR/DVL1 and miR-15b-5p/FZD6 pathways." (PMID 37723588, 2023). "MES-like glioma cells expressed multiple receptors for ANGPTL4, including syndecans SDC2, SDC3, and SDC4 as well as WNT5A receptor FZD6, suggesting that these pathways may be responsible for the enrichment of GSCs in ECMhi tumors." (PMID 37292803, 2023).
glioma (continued). "Nevertheless, it is noteworthy that miR-647, miR-767-3p, and miR-935 reportedly suppress the progression of glioma through multiple regulatory axes, including miR-647/HOXA9, miR-935/FZD6, miR-935/HIF1 α, or miR-767-3p itself, making them promising biomarkers and therapeutic targets for glioma." (PMID 34434651, 2021). "Moreover, our findings confirmed that the high expression of FZD1/2/5/6/7/8 was a disadvantageous factor in glioma, while FZD2 and FZD6 could positively serve as independent predictors of poor prognosis." (PMID 36699699, 2022).
neuroblastoma (10 papers, 2011 to 2024). Neuroblastoma (NB) is the most common solid, extracranial childhood tumor. "FZD6 is considered a potential cancer stem cell marker in human neuroblastoma and high expression is linked to a poor prognosis." (PMID 34072517, 2021). "Examples include high FZD1 expression associated with chemoresistance, FZD6 marking highly tumorigenic stem-like cells in mouse and human neuroblastoma, and FZD2-dependent proliferation of neuroblastoma lines." (PMID 29505958, 2018). "Similarly, overexpression of Fzd6, one of the Wnt receptors, was strongly associated with aggressive growth of neuroblastoma and poor patient survival." (PMID 34235142, 2021). "Moreover, FZD6, a Wnt receptor that is associated with the poor survival of neuroblastoma patients and resistance to doxorubicin, was also exclusively secreted through the exosomes." (PMID 25944692, 2015). "Here we show that expression of one such receptors, Fzd6, predicts poor survival in neuroblastoma patients and marks rare, HIF1/2 α-positive cells in tumour hypoxic areas." (PMID 22249030, 2011). "Fzd6 positive neuroblastoma cells form neurospheres with high efficiency, are resistant to doxorubicin killing and express high levels of mesenchymal markers such as Twist1 and Notch1." (PMID 22249030, 2011). "We conclude that Fzd6 is a new surface marker of aggressive neuroblastoma cells with stem cell-like features." (PMID 22249030, 2011). "Additionally, the expression of FZD6 is reported to predict poor survival in neuroblastoma patients, and marks rare and highly tumorigenic neuroblastoma stem cells." (PMID 23226679, 2012). "A Fzd6+ cell subpopulation of human neuroblastoma-derived cells was identified with the potential to form neurospheres more efficiently and invasively when compared to cells lacking Fzd6." (PMID 37804416, 2024). "When transplanted into immunodeficient mice, neuroblastoma cells expressing the Fzd6 marker grow more aggressively than their Fzd6 negative counterparts." (PMID 22249030, 2011).
gastric cancer (9 papers, 2018 to 2024). A primary or metastatic malignant neoplasm involving the stomach. "In mesenchymal glioblastoma, FZD6 is overexpressed, but in gastric cancer, overexpression of FZD6 reduced tumorigenesis." (PMID 35924166, 2022). "In gastric cancer, Wnt3A and FZD6 mediated trastuzumab resistance by activating Wnt/β-catenin pathway." (PMID 33618667, 2021). "Our results suggest that over-expression of Wnt3A and FZD6 activates the Wnt/β-catenin pathway in trastuzumab resistant gastric cancer cells, which is accompanied with EMT." (PMID 29986466, 2018). "FZD6 inhibits the proliferation and migration of gastric cancer cells." (PMID 38952556, 2024). "In contrast to other isoforms, FZD5 and FZD6 play anti-oncogenic roles in gastric cancer." (PMID 38952556, 2024). "FZD6, a member of the “frizzled” gene family, participates in the development of different human diseases, such as downregulated FZD6 repressed cell proliferative and migratory abilities in gastric cancer cells." (PMID 37554539, 2023). "With the exceptions of FZD3 and FZD6, which are expressed at low levels in gastric cancer, all FZD isoforms are highly expressed in gastric cancer cells." (PMID 38952556, 2024). "FZD6 also can inhibit the migration and proliferation of gastric cancer cells via targeting miR-21 to activate the non-classical Wnt pathway." (PMID 35859893, 2022).
melanoma (6 papers, 2004 to 2025). A malignant, usually aggressive tumor composed of atypical, neoplastic melanocytes. "Given the pro-invasion role recently identified for FZD6 in melanoma, it will be interesting to see if these miRNAs can be used for preventing melanoma progression and metastasis." (PMID 36620565, 2022). "It will be interesting to dissect the mechanistic difference between FZD3 and FZD6 in melanoma, as they clearly regulate different aspects of melanoma cell behaviors (FZD3 in cell proliferation and FZD6 in cell invasion)." (PMID 36620565, 2022). "We recently found that FZD6 is also overexpressed in multiple melanoma cell lines and patient tissues." (PMID 36620565, 2022). "Although known at a descriptive level, FZD3, FZD7, and the most recent addition of FZD6 are involved in melanoma cell survival and invasion." (PMID 36620565, 2022). "Then, we identified 9 LR pairs (“BMP6- > HJV” 、"CCL8- > ACKR4” 、"DLL3- > NOTCH3"、"DSC3- > DSG3"、"GHRH- > GHRHR” 、"LRRC4B- > PTPRF"、"SEMA4D- > PLXNB1"、"SFRP1- > FZD6"、"UCN- > CRHR1′′) as key LR pairs in melanoma prognosis through Lasso Cox regression and Multiple Stepwise Regression." (PMID 36777724, 2023). "Moreover, knockout of Fzd6 dramatically reduces lung metastasis in the Pten/BRaf mouse model of melanoma." (PMID 36620565, 2022). "Both FZD3 and FZD6 have been found to play a pro-cancer role in melanoma." (PMID 36620565, 2022). "In cancers such as melanoma, dysregulated CK1-mediated phosphorylation of FZD6 enhances PCP signaling, driving EMT and metastasis." (PMID 40376615, 2025). "We therefore chose to focus on FZD4, FZD6, and FZD8 in the further experiments and treated the LECs with either control siRNA or siRNAs targeting the FZD4, FZD6, or FZD8 gene for 24 hours before the start of the 48-hour coculture with WM852 melanoma cells, followed by sorting and functional assays." (PMID 37971882, 2024). "The structural versatility of FZD receptors, particularly FZD3, FZD5, and FZD6, enables their interaction with non-canonical Wnt ligands such as Wnt5a and Wnt11, which are often overexpressed in cancers, including breast, colorectal, and melanoma." (PMID 40376615, 2025).
Nail dysplasia (6 papers, 2012 to 2021). The presence of developmental dysplasia of the nail. "We identified a homozygous deletion mutation in FZD6 in a consanguineous Turkish family with nail dysplasia." (PMID 30642273, 2019). "Further research is needed to thoroughly understand the FZD6 function and its role in innate immunity in association with nail dysplasia." (PMID 30642273, 2019). "The importance of WNT signalling for nail development was further supported by the recent identification of FZD6 mutations in autosomal recessive nail dysplasia." (PMID 23234511, 2012). "Another study reported that Fzd6 could activate β‐catenin in patients with nail dysplasia caused by germline Fzd6 mutations, which is consistent with our results." (PMID 34056869, 2021). "It was observed that FZD6 signalling activates beta-catenin in a study of patients affected by nail dysplasia." (PMID 30642273, 2019). "Five genes have been found to be associated with nail dysplasia thus far; namely HPGD, RSPO4, PLCD1, COL7A1 and FZD6." (PMID 30642273, 2019). "Genetic analysis of FZD6 should be considered in all cases of isolated nail dysplasia." (PMID 27786367, 2016).
acute myeloid leukemia (4 papers, 2020 to 2023). Acute myeloid leukemia (AML) is a group of neoplasms arising from precursor cells committed to the myeloid cell-line differentiation. "Specifically in acute myeloid leukemia (AML), WNT10B signals through FZD4 and FZD5, while in T-cell acute lymphoblastic leukemia, WNT10B signals through FZD6." (PMID 36814601, 2023).
cervical cancer (4 papers, 2022 to 2023). A primary or metastatic malignant neoplasm involving the cervix. "In cervical cancer, silencing FZD6 function caused delayed cellular proliferation, invasion, and EMT transition through HOXC13/WNT5A/FZD6 axis." (PMID 35237656, 2022). "Additionally, FTO reduced m6A and stabilized HOXC13-AS thus up-regulating FZD6 and activating Wnt/β-catenin signaling to drive cervical cancer cell proliferation, invasion and epithelial mesenchymal transition, suggesting HOXC13-AS as a potential target for cervical cancer treatment." (PMID 37365581, 2023). "Additionally, HPV infected cervical cancer is shown to alter expression of miRNAs targeting WNT5A and FZD6." (PMID 35850748, 2022).
idiopathic pulmonary fibrosis (4 papers, 2021 to 2025). Idiopathic pulmonary fibrosis (IPF) is a nonneoplastic pulmonary disease that is characterized by the formation of scar tissue within the lungs in the absence of any known cause. "Recent work demonstrated that bone marrow-MSC-derived EVs suppress fibroblast proliferation and lung fibrosis by downregulating Frizzled Class Receptor 6 (FZD6) expression in fibroblasts through miR-29b-3p both in vitro and in vivo." (PMID 33430301, 2021). "In vitro, activation of LL29 pulmonary fibroblasts was suppressed by BM-MSC EVs and this was due to targeting of frizzled class receptor 6 (FZD6) by EV miR-29b-3p, which was also shown to be required for the inhibition by BM-MSC EVs of bleomycin-induced pulmonary fibrosis in mice." (PMID 34202136, 2021).
triple-negative breast carcinoma (4 papers, 2019 to 2024). An invasive breast carcinoma which is negative for expression of estrogen receptor (ER), progesterone receptor (PR), and human epidermal growth factor receptor 2 (HER2). "Conversely, the WNT receptor Frizzled 6 (FZD6) is frequently amplified (19.11 %) and overexpressed (18.71 %) in triple-negative breast cancer (TNBC)." (PMID 39253139, 2024).
uveal melanoma (4 papers, 2009 to 2024). A melanoma derived from melanocytes of the uveal tract. "Based on the special characteristics of uveal melanoma, namely, that it can spread only hematogenously, our aim was to further investigate the correlation between FZD6 and the genes related to angiogenesis and migration in UM." (PMID 33255843, 2020). "The biological significance of stem cell markers, such as FZD6 in primary uveal melanomas still remains unclear." (PMID 33255843, 2020).
autosomal recessive nail dysplasia (3 papers, 2012 to 2019). "Fzd6 is an essential component of the hair patterning pathway and mutation of fzd6 is known to cause autosomal-recessive nail dysplasia." (PMID 22682531, 2012). "Mutations in FZD6 gene were found to be associated with autosomal recessive nail dysplasia in 2011." (PMID 30642273, 2019).
leukemia (3 papers, 2013 to 2022). A malignant (clonal) hematologic disorder, involving hematopoietic stem cells and characterized by the presence of primitive or atypical myeloid or lymphoid cells in the bone marrow and the blood. "We report here that WNT4 cell-growth inhibition in leukemia-derived cells appears to be FZD6-independent, at least in myeloid cell lines (K562 and HL60), because this receptor is not expressed in these cells at the protein level." (PMID 24274766, 2013). "FZD6-null Eμ-TCL1 mice developed less severe leukemia than those with physiological levels of FZD6." (PMID 36612190, 2022). "Our findings suggest that the WNT4 ligand plays a role in regulating the cell growth of leukemia-derived cells by arresting cells in the G1 cell cycle phase in an FZD6-independent manner, possibly through antagonizing the canonical WNT/β-catenin signaling pathway." (PMID 24274766, 2013).
nail disorder (3 papers, 2019 to 2022). A disease involving the nail. "Pathogenic variants of five genes (RSPO4, FZD6, HPGD, PLCD1, and COL7A1) have been reported to cause congenital pure nail disorders, among which FZD6 (frizzled class receptor 6) and RSPO4 are responsible for most of the cases." (PMID 36421794, 2022). "The genes associated with human hereditary nail disorders are listed as HPGD, RSPO4, PLCD1, COL7A1 and FZD6." (PMID 30642273, 2019). "Remarkably, this family has multiple members with the classical FZD6-related nail disorder with history of NIHF during pregnancy, which suggests that FZD6-related NIHF, like THSD1-related NIHF, can be compatible with long-term survival if mortality in the newborn period is avoided." (PMID 34645488, 2021).
Anxiety (2 papers, 2022 to 2025). Intense feelings of nervousness, tension, or panic often arise in response to interpersonal stresses. "Fzd6 has also been linked to anxiety and depressive-like behavior." (PMID 40103584, 2025). "As anxiety-like behaviors correlated highly with depression, we measured these behaviors in Fzd6-KI mice with the OFT, which was measured by the number of times the mice entered or spent time in the central area." (PMID 35875672, 2022). "Consistent with our behavioral results, a previous study has shown that partial Fzd6 knockdown in the brain of rats induced anhedonic responses and anxiety, such as decreased sucrose preference, suppressed feeding, and altered performance in the EPM." (PMID 35875672, 2022). "By performing various animal behavior tests, we found the Fzd6-KI mice presented a significant increase in immobility in FST, reduced sucrose preference, and decreased locomotor activities in OFT after exposure to 10-day CSDS, suggesting these animals presented anhedonia, anxiety, or despair." (PMID 35875672, 2022).
atherosclerosis (2 papers, 2020 to 2025). A disease characterized by the build-up of fatty material and calcium deposition in the arterial wall resulting in partial or complete occlusion of the arterial lumen. "Of them, Ctnnd2, Dap, Marchf6, Cmbl, Sdc2, Cpq, Stk3, Vps13b, Cox6c, Grhl2, Fzd6, Cthrc1, Lrp12, and Zfpm2 showed associations or had functions related to atherosclerosis or obesity." (PMID 40362477, 2025). "However, the roles of FZD6 and EFEMP1 in atherosclerosis are still unclear." (PMID 32616722, 2020).
Depression (2 papers, 2016 to 2022). "In this study, to better determine the functional role of rs61753730 in depression, we generated an Fzd6-KI mouse model with rs61753730 mutation by applying the cutting-edge CRISPR/Cas9 technique, which can target even a single nucleotide." (PMID 35875672, 2022). "Specifically, we wanted to demonstrate, using various molecular techniques and behavioral tests in both in vivo and in vitro models, that non-synonymous variant rs61753730, located in the fourth exon of the FZD6, is a functional one and plays an important role in depression." (PMID 35875672, 2022). "By analyzing the expression quantitative trait loci (eQTL) dataset from GTEx Portal, we found that rs61753730 showed eQTL regulation with allele-specific significance on FZD6 mRNA expression, especially in the cerebellum (p = 1.3 × 10–5), a brain region implicated in depression." (PMID 35875672, 2022). "Luckily, our current study discovered a missense SNP rs61753730 in FZD6 that is significantly associated with depression, in which the person who carries rs61753730-G (the risk allele) may have an increased risk for depression." (PMID 35875672, 2022). "To further investigate the biological role of rs61753730 on FZD6 in depression, we carried out in silico analysis and found that the different alleles of rs61753730 lead to an altered protein configuration." (PMID 35875672, 2022). "To define the biological role of SNP rs61753730 in the regulation of FZD6 in depression, we carried out a series of investigations at different levels." (PMID 35875672, 2022). "Consistent with our results, knockdown of Fzd6 by injection of shRNA virus into the hippocampus resulted in depression-like behaviors in SPT." (PMID 27622936, 2016). "However, the genetic and mechanistical studies on FZD6 in depression are rare." (PMID 35875672, 2022). "Taken together, these behavioral results strongly indicated that the Fzd6-KI mice presented depressive symptoms like those in WT mice subjected to CSDS, suggesting an important role of rs61753730 in depression." (PMID 35875672, 2022).